SMARCA4 (SWI/SNF related BAF chromatin remodeling complex subunit ATPase 4)
Diseases named in the same sentence as SMARCA4 in open-access papers (continued):
Sharing a sentence is not in itself a finding about the gene and the disease.
leukemia (20 papers, 2009 to 2025). A malignant (clonal) hematologic disorder, involving hematopoietic stem cells and characterized by the presence of primitive or atypical myeloid or lymphoid cells in the bone marrow and the blood. "For example, in a previous study, SMARCA4 had been reported to promote the expression of the MYC oncogene specifically in leukemia, even though both MYC and SMARCA4 are expressed ubiquitously across many cell types." (PMID 36810086, 2023). "Inactivating mutations of BRG1/SMARCA4, SNF5/SMARCB1, BCL11B, and the BAF complex subunits SMARCA2 and ARID1A are prevalent in leukemia." (PMID 33468999, 2021). "The following sections summarize the eight top-ranked genes in some of the major drug classes (FLT3, CASP8AP2, L2HGDH, MNT, BAZ2B, MZF1, BEX2, and SMARCA4) that are highly likely to have notable biological significance in leukemia." (PMID 29298978, 2018). "In order to assess the effect of SWI/SNF complex subunits Smarca4, Smarcd2 or Dpf2 depletion in leukaemia, we transduced MLL-AF9 transformed mouse spleen cells with viruses expressing shRNA target sequences against the genes of each subunit." (PMID 26571505, 2015). "For example, recent reports have observed that while in most of the tumor types studied, SMARCA4 is known to have a tumor suppressive function, leukemia cells instead rely on SMARCA4 to support their oncogenic transcriptional program." (PMID 25391308, 2014). "Therefore, precise targeting of SMARCA4 in leukemia treatment may have specific therapeutic effects." (PMID 40342423, 2025). "In summary, during lymphocyte differentiation, SMARCA4 and SMARCA2 affect lymphocytic function and the development of related diseases, especially leukemia and lymphoma, by enhancing chromatin accessibility and interacting with various TFs." (PMID 40342423, 2025). "In leukemia, the core ATPase subunits are BRG/SMARCA4 and BRM/SMARCA2, where BRG/SMARCA4 is essential for the proliferation of both normal hematopoietic stem cells and leukemia stem cells." (PMID 29298978, 2018). "Here we further explore the role of SMARCA4 and the two SWI/SNF subunits SMARCD2/BAF60B and DPF2/BAF45D in leukaemia." (PMID 26571505, 2015). "The BAF complex, driven by BRG1 (SMARCA4) or BRM (SMARCA2), enables transcription factors such as PU.1 and MYC to bind enhancers and promoters, sustaining oncogenic transcriptional programs essential for leukemia cell survival." (PMID 39682203, 2024). "To assess the relevance of our observations in a physiological context, we transplanted sublethally-irradiated mice with MLL-AF9 cells transduced with shRNAs targeting either Smarca4, Smarcd2, Dpf2, or non-targeting control (shScr) and monitored mice for the onset of leukaemia." (PMID 26571505, 2015).
medulloblastoma (19 papers, 2012 to 2025). A malignant, invasive embryonal neoplasm arising from the cerebellum. "For example, decreased SMARCA4 expression is linked to medulloblastoma and different brain cancers, from low-grade gliomas to glioblastoma." (PMID 38542211, 2024). "SMARCA4 has been implicated in the genetic and epigenetic network that plays an important role in medulloblastoma tumor development and growth." (PMID 39160595, 2024). "Medulloblastomas (MB), the most common malignant pediatric brain tumors, mainly show somatic heterozygous missense mutations of SMARCA4, which are suggested to have a dominant-negative effect resulting in a loss of function." (PMID 37919824, 2023). "Altogether, the development of SMARCA4-deficient medulloblastomas in mice paves the way to deciphering the role of frequently occurring SMARCA4 alterations in Group 3 medulloblastoma with the perspective to explore targeted therapeutic options." (PMID 37919824, 2023). "While overexpression of MYC has previously been shown to drive medulloblastoma formation in mice, the functional significance of SMARCA4 mutations and their suitability as a therapeutic target remain largely unclear." (PMID 37919824, 2023). "In other tumor types, such as Burkitt lymphoma or medulloblastoma (MB), heterozygous missense mutations in SMARCA4 have been identified, but their role in tumor development remains elusive." (PMID 33331994, 2021). "Loss-of-function SWI/SNF subunit mutations seem most prevalent in cancer, i.e., SCCOHT, NSCLC, point mutations have also been described, such as a small number of SMARCA4 missense mutations in medulloblastoma." (PMID 26075616, 2015). "SMARCA4 mutations are also frequently found in the WNT group and group III subgroups of medulloblastomas, with group III being the subgroup with the earliest age of incidence and worst prognoses." (PMID 38427725, 2024). "SMARCA4 overexpression reduced OM-induced medulloblastoma but was less effective against GM-induced medulloblastoma." (PMID 39062993, 2024). "Its mutant, SMARCA4 T910M, counteracted the functions of the wild-type protein in medulloblastoma patients." (PMID 36831595, 2023). "BRG1/SMARCA4 is mutationally inactivated or epigenetically silenced in non-small-cell lung cancer (NSCLC), medulloblastoma, and Burkitt’s lymphoma." (PMID 33419967, 2021). "Furthermore, heterozygous aberrations of SMARCA4 are findings typically observed in other pediatric brain tumors, such as medulloblastoma." (PMID 41168858, 2025). "Mutations in SMARCA4 or SMARCB1 (which encodes the core subunit BAF47) can give rise to highly aggressive pediatric brain tumors such as atypical teratoid/rhabdoid tumors (ATRTs) and medulloblastomas." (PMID 38427725, 2024). "The overexpression of SMARCA4 reduced medulloblastoma expression." (PMID 39062993, 2024). "In comparing the transcriptome of tumors to the cells of origin and an established Sonic Hedgehog medulloblastoma model, we gathered first hints on deregulated gene expression that could be specifically involved in SMARCA4/MYC driven tumorigenesis." (PMID 37919824, 2023). "Furthermore, the study reported that SMARCA4 overexpression thwarted OM-induced Group 3 medulloblastoma in vivo and in cerebellar organoids." (PMID 36831595, 2023). "In contrast, medulloblastoma (MB) samples with heterozygous SMARCA4 mutations do not group separately, but with established MB subgroups." (PMID 33331994, 2021). "These alterations in medulloblastomas seem to be entirely somatic and it is not clear whether their mechanism of action parallels tumorigenesis in SMARCA4 -/- tumors." (PMID 41168858, 2025).
triple-negative breast carcinoma (18 papers, 2016 to 2024). An invasive breast carcinoma which is negative for expression of estrogen receptor (ER), progesterone receptor (PR), and human epidermal growth factor receptor 2 (HER2). "SMARCA4 mutations were over-representative in cisplatin resistance and metastatic triple-negative breast cancer (TNBC)." (PMID 34771636, 2021). "Mutated in 20% of human cancers; doxorubicin resistant triple-negative breast cancer is associated with loss of SMARCB1, SMARCA4, or KEAP1 (a BRCA1 interactor)." (PMID 31287417, 2019). "Additionally, it was observed that both BRG1 and BRM are required for the triple-negative breast cancer (TNBC) proliferation and that double SMARCA2 and SMARCA4 knock-down results in slowed tumour growth in xenografts." (PMID 31722744, 2019).
uterine sarcoma (18 papers, 2020 to 2025). "SMARCA4-deficient uterine sarcoma (SDUS) is a rare and highly aggressive uterine malignancy defined by the inactivation or loss of the SMARCA4 gene, a key component of the SWI/SNF chromatin remodeling complex." (PMID 41463261, 2025). "Together, these tumours form a DNA methylation cluster separate from uterine smooth muscle tumours (leiomyomas and leiomyosarcomas), endometrial stromal sarcomas (low-grade and high-grade), embryonal rhabdomyosarcoma and SMARCA4-deficient uterine sarcomas." (PMID 41424301, 2025). "Clinical data of SMARCA4-deficient undifferentiated uterine sarcoma were reported in the literature." (PMID 40826772, 2025). "The SWI/SNF-related, matrix-associated, actin-dependent regulator of chromatin, subfamily A, member 4 (SMARCA4)-deficient uterine sarcoma is a unique, recently discovered subtype of uterine sarcoma, with nearly 30 cases reported in the literature." (PMID 39064514, 2024). "SMARCA4-deficient uterine sarcoma (SDUS) is a monogenic cancer distinguished by its rapid invasiveness resulting from the inactivation of the SMARCA4 gene." (PMID 39199375, 2024). "SMARCA4-deficient undifferentiated uterine sarcoma (SDUS) is a highly aggressive undifferentiated uterine sarcoma caused by a SMARCA4 deletion." (PMID 37194064, 2023). "This leaves only 2 SWI/SNF‐deficient UEC in this cohort of SWI/SNF‐deficient DDEC/UEC with potential overlap with SMARCA4‐deficient uterine sarcoma." (PMID 33125840, 2021). "Aside from the demonstration of MMR protein deficiency that favors UEC, there are currently no reliable immunohistochemical markers that can be used to differentiate between SMARCA4‐deficient (and MMR protein‐intact) UEC from SMARCA4‐deficient uterine sarcoma." (PMID 33125840, 2021). "It is worth noting that the recently described SMARCA4‐deficient uterine sarcoma (malignant rhabdoid tumor of the uterus) can share histologic, immunophenotypic and genetic overlap with the undifferentiated component of DDEC or UEC." (PMID 33125840, 2021). "Recent genomic studies have identified loss of SMARCA4 in undifferentiated uterine sarcomas and dedifferentiated carcinomas of the endometrium or ovary." (PMID 32972432, 2020). "Two cases diagnosed as HG-ESS were reclassified as UUS, and three cases diagnosed as UUS were reclassified either as HG-ESS (n = 1), NTRK fusion-positive uterine sarcomas (n = 1) or SMARCA4-deficient uterine sarcoma (n = 1)." (PMID 32933053, 2020). "For example, in combination with a panel of other molecular features, SMARCA4 has become a novel tool to discern between SMARCA4-deficient undifferentiated uterine sarcoma and undifferentiated and dedifferentiated endometrial carcinomas (generally expressing intact SMARCA4)." (PMID 34771683, 2021). "However, ARID1B loss has not yet been reported in pediatric and young adult undifferentiated malignancies, such as SCCOHT and SMARCA4-deficient uterine sarcoma (SDUS), or malignant rhabdoid tumors of the kidney (MRT), and atypical teratoid rhabdoid tumor (ATRT)." (PMID 37686505, 2023). "Similarly, UUS reclassified as SMARCA4-deficient uterine sarcoma (CLB_RNA_426), also called “malignant rhabdoid tumor of the uterus”, is a candidate to anti-PD1 in a clinical trial given the high response rates to immunotherapy in this entity (ClinicalTrials.gov Identifier: NCT03012620)." (PMID 32933053, 2020). "Dual loss of both the SMARCA4 and the SMARCA2 occurs in SCCOHT and in other neoplasms such as thoracic sarcomas, undifferentiated and dedifferentiated endometrial carcinomas, and rare undifferentiated uterine sarcomas." (PMID 35200537, 2022). "Genetic alterations in the Switch/Sucrose Non-Fermentable (SWI/SNF) chromatin remodeling complex components, such as SMARCA4 and BCOR, are recently reported in young high-grade uterine sarcomas, but their relationship with adenosarcomas remains unknown." (PMID 32972432, 2020).
liver fibrosis (17 papers, 2019 to 2026). "In the present study we investigated the mechanism by which Brahma-related gene 1 (BRG1, encoded by Smarca4) regulates HSC-myofibroblast transition and the implication in intervention against liver fibrosis." (PMID 38092723, 2023).
sinonasal carcinoma (17 papers, 2021 to 2026). "SMARCA4-deficient sinonasal carcinomas mainly arose in the nasal cavity (3 of 4 patients), characterized by nasal obstruction (4 of 6 patients), and epistaxis or purulent rhinorrhea (4 of 6 patients); ocular symptoms were less common (2 of 6 patients)." (PMID 42074742, 2026). "The sinonasal tract is a recognized "hot-spot" for SMARCA4-deficient cancers, including SMARCA4-deficient sinonasal carcinomas, and most sinonasal teratocarcinosarcomas." (PMID 41803273, 2026). "SMARCA4-deficient sinonasal carcinoma is even rarer, with fewer than 22 cases reported since the first report in 2017." (PMID 40366517, 2025). "Sinonasal carcinoma with SMARCA4‐deficiency have been documented as a rare entity that appears to show a much more aggressive clinical course." (PMID 39359021, 2025). "SMARCB1-deficient and SMARCA4-deficient sinonasal carcinomas are rare, with only a few systematic studies available in the literature." (PMID 40366517, 2025). "In the sinonasal tract, primarily two neoplasms deficient in SMARCA4 have been reported—SMARCA4-deficient sinonasal carcinoma and SMARCA4-deficient sinonasal teratocarcinosarcoma." (PMID 39590317, 2024). "SMARCA4-deficient sinonasal carcinomas are a type of poorly differentiated or undifferentiated tumor, which are locally very aggressive and have a poor short-term prognosis—these are characteristics shared with sinonasal undifferentiated carcinoma (SNUC)." (PMID 39590317, 2024). "The mortality of SMARCA4-deficient sinonasal carcinomas is higher than in other tumors of this family." (PMID 38217715, 2024). "One distinguishing difference between this group of lethal carcinomas and SMARCA4-deficient sinonasal carcinomas is IDH2 mutation." (PMID 39590317, 2024). "A complete loss of SMARCB1 (testing INI1]) and SMARCA4 (testing BRG1) reactivity in the tumor nuclei is essential for the diagnosis of SMARCB1-deficient and SMARCA4-deficient sinonasal carcinoma, respectively." (PMID 36941503, 2023). "There are several recently discovered distinct entities, such as SMARCA4 deficient sinonasal carcinomas and SMARCB1 (INI-1) deficient sinonasal carcinoma." (PMID 37568614, 2023). "SMARCA4-deficient sinonasal carcinoma behaves more aggressively compared to the SMARCB1-deficient tumors; two thirds of patients with follow-up died of their disease within one year." (PMID 35307773, 2022). "They particularly suggest that TCS is on a spectrum with SMARCA4-deficient sinonasal carcinomas which show overlapping morphology and molecular characteristics, further readjusting the classification of high-grade sinonasal tumors." (PMID 36431263, 2022). "Contrasting with their SMARCB1-deficient counterparts, the basaloid small cell pattern is much infrequent in SMARCA4-deficient sinonasal carcinomas." (PMID 35307773, 2022). "Among them, 16 were SNUCs, four SMARCB1-deficient sinonasal carcinomas, one SMARCA4-deficient carcinoma, five high-grade neuroendocrine carcinomas, one NC, one TCS, and two sinonasal N-ITAC." (PMID 36431263, 2022). "SMARCA4 (BRG1)-deficient sinonasal carcinoma represents another uncommon tumor subtype where the SWI/SNF chromatin-remodeling complex is aberrated." (PMID 35059992, 2022). "SMARCA4-deficient sinonasal carcinomas lack differentiated features, both histologically (absence of glands, squamous cells, and others) and immunohistochemically (lack of squamous cell marker expression)." (PMID 35307773, 2022). "SMARCA4-deficient sinonasal carcinomas represented 4% of poorly differentiated/undifferentiated epithelial-derived sinonasal malignancies, 9% of all SNUCs, and 20% of IDH2-wildtype SNUC." (PMID 35307773, 2022). "SMARCA4-deficient sinonasal carcinoma is a very infrequent tumor, previously rendered as a SNUC, with very few cases reported so far." (PMID 34638515, 2021).
sinonasal carcinoma (continued). "There are four different subtypes of SWI/SNF complex deficient sinonasal/base of skull malignancies, including SMARCB1-deficient sinonasal carcinoma, SMARCB1-deficient sinonasal adenocarcinoma, SMARCA4-deficient sinonasal carcinoma, and a subset of SMARCA4-deficient teratocarcinosarcomas." (PMID 38491228, 2024). "Being unified by SMARCA4 loss, TCS and SMARCA4-deficient sinonasal carcinoma might be looked at as different morphotypes on the spectrum of same entity rather than two independent entities." (PMID 35307773, 2022). "In most cases, SMARCA4-deficient sinonasal carcinoma lacks the classical nuclear and chromatin characteristics of true neuroendocrine carcinomas, but they display frequently focal or diffuse but usually weak and heterogeneous expression of the neuroendocrine markers." (PMID 35307773, 2022). "It is debatable whether the cases of the tumors derived from ethmoid sinus should be diagnosed with NEC or SMARCA4-deficient sinonasal carcinoma." (PMID 34247193, 2021). "Indeed, molecularly distinct subtypes of sinonasal carcinomas, including SMARCB1-INI1 or SMARCA4 deficient sinonasal carcinoma, isocitrate dehydrogenase (IDH)-mutant SNUC, ARID1A mutant PDSNCs, and NUT carcinomas, have recently been proposed as separate entities." (PMID 34638515, 2021). "Among the subunits that have been studied extensively (SMARCB1, SMARCA4, SMARCA2, and ARID1A), the loss of SMARCB1 and SMARCA4 has been implicated in sinonasal carcinomas." (PMID 40366517, 2025). "SWI/SNF complex-deficient sinonasal carcinomas are now well recognized as high-grade malignancies with distinctive deficiencies in the SMARCB1 and SMARCA4 subunits, distinguishing them from other neoplasms such as SNUC or poorly differentiated carcinomas." (PMID 39590317, 2024). "SMARCB1-deficient carcinomas account for 4.7% of sinonasal carcinomas in this single-institution cohort, while SMARCA4-deficient tumors are even rarer, with none identified." (PMID 40366517, 2025). "SMARCB1-deficient sinonasal carcinomas constitute 4.7% of sinonasal carcinomas in our cohort; and none were SMARCA4-deficient carcinomas." (PMID 40366517, 2025). "SWI/SNF complex-deficient sinonasal carcinoma, defined by the loss of SMARCB1 or SMARCA4, was recently recognized as a distinct entity in the 5th edition of the World Health Organization (WHO) Classification of Head and Neck Tumors, highlighting its unique clinicopathologic and molecular profile." (PMID 40366517, 2025). "SMARCB1-deficient sinonasal carcinomas account for 4.7% of carcinomas of the sinonasal tract in this single-institution cohort, while no cases of SMARCA4-deficient sinonasal carcinoma were identified." (PMID 40366517, 2025). "Sinonasal carcinomas characterized by rhabdoid/basaloid morphology and loss of expression of the SWI/SNF complex (SMARCB1, SMARCA4, SMARCA2), previously viewed as a subset of SNUCs, are recognized as a standalone entity in the 5th edition WHO Classification of Head and Neck Tumours." (PMID 38315310, 2024). "Since the first detailed description by Agaimy and Weichert, no more than 22 cases of SMARCA4-deficient sinonasal carcinoma have been reported in the literature." (PMID 38491228, 2024). "SMARCA4 deficient carcinoma is thought to have a neuroendocrine origin, while SMARCB1 deficient carcinoma represents an emerging poorly differentiated/undifferentiated sinonasal carcinoma." (PMID 37568614, 2023). "It is the small blue cell (olfactory-like) pattern in the spectrum of SMARCA4-deficient sinonasal carcinoma that might be indistinguishable from TCS on limited biopsy material." (PMID 35307773, 2022). "Indeed, molecularly distinct subtypes of sinonasal carcinomas, including SMARCB1-INI1 or SMARCA4 deficient sinonasal carcinoma, isocitrate dehydrogenase (IDH)-mutant SNUC, ARID1A mutant PDSNCs, and NUT carcinomas (harboring NUT-variant fusions), have recently been proposed as separate entities." (PMID 34638515, 2021).
sinonasal carcinoma (continued). "Of the 149 sinonasal carcinomas, 7 (4.7%) showed SMARCB1 loss, while none demonstrated SMARCA4 loss." (PMID 40366517, 2025). "Among the 149 sinonasal carcinomas analyzed, SMARCB1 (INI1) expression was lost in 7 tumors (4.7%) (95% confidence interval: 1.7–10.3%), while none showed loss of SMARCA4 (BRG1) expression by immunohistochemical staining (0/149) (95% confidence interval: 0 to 4.6%)." (PMID 40366517, 2025).